ATP5MC3 (ATP synthase membrane subunit c locus 3)
Description:
Mitochondrial membrane ATP synthase (F(1)F(0) ATP synthase or Complex V) produces ATP from ADP in the presence of a proton gradient across the membrane which is generated by electron transport complexes of the respiratory chain. F-type ATPases consist of two structural domains, F(1) - containing the extramembraneous catalytic core and F(0) - containing the membrane proton channel, linked together by a central stalk and a peripheral stalk. During catalysis, ATP synthesis in the catalytic domain of F(1) is coupled via a rotary mechanism of the central stalk subunits to proton translocation. Part of the complex F(0) domain. A homomeric c-ring of probably 10 subunits is part of the complex rotary element.
Synonyms: ATP5G3; DYTSPG; P3
Tractability: Antibody: UniProt predicts a signal peptide or a membrane-spanning region. PROTAC: ubiquitination databases record sites on it.
Gene: Protein-coding gene on chromosome 2 (175,176,258 to 175,181,764, reverse strand). Ensembl gene ENSG00000154518.
Subcellular location: Mitochondrion membrane
Pathways (Reactome):
Metabolism: Formation of ATP by chemiosmotic coupling
Organelle biogenesis and maintenance: Cristae formation
Gene Ontology:
Molecular function: protein binding; proton transmembrane transporter activity
Biological process: proton motive force-driven ATP synthesis; proton transmembrane transport
Cellular component: mitochondrion; mitochondrial inner membrane; proton-transporting ATP synthase complex; mitochondrial membrane; proton-transporting two-sector ATPase complex, proton-transporting domain
Genetic constraint (gnomAD): Loss-of-function variants: 5 observed, 12.35 expected, observed/expected ratio (o/e) 0.4, 90% interval 0.21 to 0.85. The upper end of that interval is the gene's LOEUF score, 0.85, which puts it in group 3 of 6, group 1 being the genes least tolerant of losing a copy. Missense variants: 121 observed, 169.15 expected, observed/expected ratio (o/e) 0.72, 90% interval 0.62 to 0.83. Synonymous variants: 65 observed, 62.9 expected, observed/expected ratio (o/e) 1.03, 90% interval 0.85 to 1.27.
Gene-disease validity (ClinGen):
ClinGen rates the evidence that ATP5MC3 causes each of these diseases.
mitochondrial disease (autosomal dominant): Limited.
Homologues: Orthologues: chimpanzee ATP5MC3 (100% identical), macaque ATP5MC3 (99% identical), rabbit ATP5MC3 (98% identical), guinea pig ATP5MC3 (96% identical), pig ATP5MC3 (96% identical), mouse Atp5mc3 (95% identical), rat Atp5mc3 (95% identical), dog ATP5MC3 (94% identical), tropical clawed frog atp5mc3 (85% identical), zebrafish atp5mc3a (80% identical). Paralogues in human: ATP5MC2 (75% identical), ATP5MC1 (69% identical).
Diseases named in the same sentence as ATP5MC3 in open-access papers:
ATP5MC3 is named in the same sentence as 26 diseases in open-access papers, as found by Europe PMC text mining. Sharing a sentence is not in itself a finding about the gene and the disease. The quoted sentences say what the papers report.
colon cancer (4 papers, 2021 to 2023). "Further analysis of the 18 ferroptosis-colon cancer co-associated genes, excluding ATP5MC3, revealed significant correlations and protein-protein interactions." (PMID 37304867, 2023). "High ATP5MC3 expression predicted a poor prognosis in prostate cancer, colon cancer, and endometrial cancer." (PMID 35509981, 2022). "However, ATP5MC3 and FDFT1 were protective genes for colon cancer patients." (PMID 34046350, 2021).
melanoma (2 papers, 2022). A malignant, usually aggressive tumor composed of atypical, neoplastic melanocytes. "In contrast, ALOX5, CISD1, ATP5MC3, NFS1, EMC2, ZEB1 are highly expressed in normal tissues, and they are related to the good prognosis of melanoma patients." (PMID 36313708, 2022).
prostate carcinoma (2 papers, 2022). A carcinoma that arises from epithelial cells of the prostate gland. "ATP5MC3 is better predictor in a risk prognosis model and also be defined as potential drug for treatment of prostate cancer." (PMID 35309947, 2022).
Dystonia (1 paper, 2024). An abnormally increased muscular tone that causes fixed abnormal postures. "In this regard, a novel variant in ATP5MC3 co-segregated with both dystonia and spastic paraplegia in a large multiplex pedigree." (PMID 39262575, 2024).
viral infection (1 paper, 2025). "Mitochondrial components, including the inner and outer membranes, were highly enriched (e.g. ATP5MC3, COX6B1 and SLC25A38; adjusted P<0.01), underscoring the role of mitochondrial reprogramming during viral infection." (PMID 40989927, 2025).
tumor (13 papers, 2015 to 2024). "For example, the expression of SLC7A11, FANCD2, and CISD1 was higher in tumor tissues than that in normal tissues, but ATP5MC3 was lower." (PMID 35309947, 2022). "Of note, our results showed that ATP5MC3, CDKN1A, and SLC7A11 expression was dramatically positively related with the tumor mutational burden (TMB) score in EC." (PMID 34531924, 2021). "Our findings revealed that certain FRGs (CISD1, ATP5MC3, PGD, SLC7A11, ACSL3, and FANCD2) are significantly upregulated in LUAD and that their elevated expression is associated with both advanced tumor stage and unfavorable prognosis." (PMID 35320929, 2021). "Analysis of gene expression, mutation, DNA methylation, and prognostic value in LUAD revealed CISD1, ATP5MC3, PGD, SLC7A11, ACSL3, and FANCD2 to be significantly upregulated in LUAD and elevated expression of these FRGs to be associated with advanced tumor stage and poor prognosis." (PMID 35320929, 2021). "Finally, CISD1, ATP5MC3, PGD, SLC7A11, ACSL3, and FANCD2 expression was confirmed to significantly correlate with tumor mutational burden (TMB), microsatellite instability (MSI), immune cell infiltration, cellular checkpoint dysfunction, and cancer sensitivity to drugs." (PMID 35320929, 2021). "The upstream lncRNA GSEC/miRNA-101-3p regulatory axis involving CISD1, ATP5MC3, and PGD was identified to be relevant in tumor progression." (PMID 35320929, 2021). "As ferroptosis plays crucial roles in both immunity and pulmonary carcinogenesis, the correlation between CISD1, FANCD2, PGD, ASCL3, ATP5MC3, and SLC7A11 expression and tumor immune infiltration in LUAD was evaluated utilizing data obtained from the TIMER database." (PMID 35320929, 2021).
cancer (5 papers, 2016 to 2022). A tumor composed of atypical neoplastic, often pleomorphic cells that invade other tissues. "Meanwhile, four of the FRGs, ATP5MC3, HMGCR, CARS1, and PHKG2, are strongly related to the competitive endogenous RNA (ceRNA) network, which has become more and more popular in cancer research nowadays." (PMID 34868393, 2021). "Reports on the correlation of ATP5MC3 (also known as P3 and ATP5G3) with cancer are lacking." (PMID 34170849, 2021).
infection (2 papers, 2013 to 2022). The state of being infected such as from the introduction of a foreign agent such as serum, vaccine, antigenic substance or organism. "In response to infection, in male mice, the TACC2, BUB1B, ATP5MC3, and MYO1E, and in female mice, the CAP1, MRPL2, COX5A, KLHL21, PDIA6, TSPO, and USP14 had direct interaction with TP-53." (PMID 35844510, 2022).
ATP5MC3 also shares sentences with these, for which no sentence is quoted: Alzheimer disease (1 paper); autism (1); cerebral malaria (1); chronic heart failure (1); clear cell renal carcinoma (1); colitis (1); colorectal cancer (1); endometrial cancer (1); glioma (1); hypertrophic cardiomyopathy (1); ischemia (1); malaria (1); neuroblastoma (1); neurodegenerative disease (1); papillary thyroid carcinoma (1); Parkinson disease (1); Spastic paraplegia (1); tendinopathy (1).